DNAJC24 (DnaJ heat shock protein family (Hsp40) member C24)
Description:
Stimulates the ATPase activity of several Hsp70-type chaperones. This ability is enhanced by iron-binding. The iron-bound form is redox-active and can function as electron carrier. Plays a role in the diphthamide biosynthesis, a post-translational modification of histidine which occurs in translation elongation factor 2 (EEF2) which can be ADP-ribosylated by diphtheria toxin and by Pseudomonas exotoxin A (Eta).
Synonyms: DPH4; ZCSL3; JJJ3
Tractability: PROTAC: ubiquitination databases record sites on it; its protein half-life has been measured.
Gene: Protein-coding gene on chromosome 11 (31,369,840 to 31,432,835, forward strand). Ensembl gene ENSG00000170946.
Subcellular location: Cytoplasm, cytoskeleton
Subcellular location (Human Protein Atlas): Cytosol
Pathways (Reactome):
Metabolism of proteins: Synthesis of diphthamide-EEF2
Gene Ontology:
Molecular function: ATPase activator activity; ferrous iron binding; zinc ion binding
Biological process: positive regulation of ATP-dependent activity; protein folding; protein histidyl modification to diphthamide
Cellular component: actin cytoskeleton; cytoskeleton
Genetic constraint (gnomAD): Loss-of-function variants: 9 observed, 10.28 expected, observed/expected ratio (o/e) 0.88, 90% interval 0.53 to 1.51. The upper end of that interval is the gene's LOEUF score, 1.51, which puts it in group 6 of 6, group 1 being the genes least tolerant of losing a copy. Missense variants: 77 observed, 94.24 expected, observed/expected ratio (o/e) 0.82, 90% interval 0.68 to 0.99. Synonymous variants: 30 observed, 32.51 expected, observed/expected ratio (o/e) 0.92, 90% interval 0.69 to 1.25.
Homologues: Orthologues: chimpanzee DNAJC24 (100% identical), rabbit DNAJC24 (86% identical), mouse Dnajc24 (83% identical), rat Dnajc24 (82% identical), guinea pig DNAJC24 (74% identical), pig DNAJC24 (70% identical), zebrafish dnajc24 (49% identical), Caenorhabditis elegans dnj-8 (21% identical), Drosophila melanogaster l(3)80Fg (21% identical), Drosophila melanogaster CG10565 (19% identical), Caenorhabditis elegans dnj-2 (15% identical), Caenorhabditis elegans dnj-7 (15% identical), and 4 more. Paralogues in human: DNAJC13 (32% identical), DNAJC16 (25% identical), DNAJC5 (25% identical), DNAJC21 (24% identical), DNAJC5B (24% identical), DNAJC12 (23% identical), DNAJC18 (23% identical), DNAJC11 (21% identical), DNAJC10 (21% identical), DNAJC14 (20% identical), DNAJC17 (19% identical), DNAJC2 (19% identical), and 8 more.
Diseases named in the same sentence as DNAJC24 in open-access papers:
DNAJC24 is named in the same sentence as 8 diseases in open-access papers, as found by Europe PMC text mining. Sharing a sentence is not in itself a finding about the gene and the disease. The quoted sentences say what the papers report.
aniridia (2 papers, 2011 to 2023). Aniridia is a congenital ocular malformation characterized by the complete or partial absence of the iris. "In this study, the novel 517 kb heterozygous deletion (chr11:31,139,019–31,655,997) downstream of PAX6 containing four annotated genes, DCDC1, DNAJC24, IMMP1L, and ELP4, is likely to be the cause of the familial aniridia in this Chinese family." (PMID 37752489, 2023). "Taken together, a 517 kb heterozygous deletion containing four annotated genes, DCDC1, DNAJC24, IMMP1L, and ELP4, was identified in this Chinese family with congenital aniridia, suggesting that transcription-regulating elements in the deleted region are required for the expression of PAX6." (PMID 37752489, 2023). "Recently a ~406 kb heterozygous genomic deletion containing four annotated genes (DCDC1, DNAJC24, IMMP1L, and ELP4) was found in patients with aniridia; apparently the gene contents in this deletion are the same as the 566 kb heterozygous deletion in the family we report here." (PMID 21321669, 2011).
hepatocellular carcinoma (2 papers, 2022). A malignant tumor that arises from hepatocytes. "Our study confirmed for the first time that DNAJC24 can affect autophagy in hepatocellular carcinoma by interfering with ammonia metabolism." (PMID 35606363, 2022). "To evaluate the role of DNAJC24 in the progression of HCC, we first analyzed that DNAJC24 mRNA expression was significantly upregulated in tumors compared with normal tissues based the TCGA Liver Hepatocellular Carcinoma dataset (n = 50)." (PMID 35606363, 2022). "Here we demonstrated for the first time that high expression of DNAJC24 (a heat shock protein) shortens survival in patients with HCC by immunohistochemical staining of 167 paired hepatocellular carcinomas and paraneoplastic tissues as well as data from public databases." (PMID 35606363, 2022). "Recently, Guo and his colleagues showed that high expression of DNAJC24 (HSP40 Member C24, a heat shock protein) occurs in hepatocellular carcinoma patients with shortened life span and that the transcription of DNAJC24 is regulated by HSF2." (PMID 36430241, 2022). "High expression of DNAJC24 was observed in hepatocellular carcinoma cells but not in nonmalignant cells." (PMID 36430241, 2022).
osteosarcoma (1 paper, 2015). A usually aggressive malignant bone-forming mesenchymal neoplasm, predominantly affecting adolescents and young adults. "Across all Ewing and osteosarcoma cell lines eleven genes were found to be either significantly (P < 0.05, Bonferroni correction) repressed (KIF20A, IDH1, SCD, GPSM2, EIF2AK4, HIBCH) or induced (STK19, DNAJC24, MTG2, FAM175B, CYB5D1) following non DNA-damaging XI-006 treatment (0.5 μM)." (PMID 26095524, 2015).
tumor (3 papers, 2010 to 2022). "The protein expression of DNAJC24 were also significantly higher in tumor than in corresponding non-tumor tissues." (PMID 35606363, 2022). "By immunohistochemistry staining of 167 HCC tissues, we found that the expression of DNAJC24 correlated with tumor size and vessel density." (PMID 35606363, 2022). "Taken together, by using IHC staining of a large number of HCC tissues and online database, we found that DNAJC24 expression was elevated in HCC tissues and was an independent risk factor for HCC prognosis, while DNAJC24 expression levels correlated with tumor size and microvessel density." (PMID 35606363, 2022). "Next, we examined the protein expression of DNAJC24 in 167 paired HCC and non-tumor samples by IHC assays to further identify the effect of DNAJC24 on the prognosis of HCC." (PMID 35606363, 2022).
DNAJC24 also shares sentences with these, for which no sentence is quoted: autism (1 paper); breast carcinoma (1); Miller-Dieker syndrome (1); ovarian carcinoma (1).